PHF6 (PHD finger protein 6)
Diseases named in the same sentence as PHF6 in open-access papers (continued):
Sharing a sentence is not in itself a finding about the gene and the disease.
cancer (22 papers, 2012 to 2025). A tumor composed of atypical neoplastic, often pleomorphic cells that invade other tissues. "Our data showed that PHF6 protein and associated molecules lead to the activation of canonical pathways involved in expression of RNA and cancer progression by interaction with several oncogenes." (PMID 38790189, 2024). "While such mutations were first identified in severe developmental disorders, or in specific cancers, several genes have been implicated in both, including the plant homeodomain finger protein 6 (PHF6) gene." (PMID 26103525, 2015). "Our study found that PHF6 was negatively associated with immune infiltration in most cancers." (PMID 41515604, 2025). "Moreover, PHF6 expression was strongly associated with prognosis, immune cell infiltration, and the expression of immune checkpoint genes in various cancers." (PMID 41515604, 2025). "Additionally, PHF6 expression was positively associated with the expression of RNA m1A modification-related genes in the majority of cancers." (PMID 41515604, 2025). "Somatic PHF6 mutations have been found in haematological cancer and may play a role in other cancer types." (PMID 37704779, 2023). "In addition, we explored the association between PHF6 and immune checkpoint genes in pan-cancer." (PMID 41515604, 2025). "Utilizing the TCGA Pan-Cancer dataset, we calculated the immune infiltration score for each sample and analyzed the correlation between PHF6 and immune infiltration." (PMID 41515604, 2025). "PHF6 was positively correlated with resting memory CD4+ T cells across many cancer types but negatively correlated with activated NK cells." (PMID 41515604, 2025). "We employed univariate Cox regression analysis to examine the association between PHF6 levels and prognosis across various cancers to evaluate the prognostic role of PHF6." (PMID 41515604, 2025). "In conclusion, bioinformatic analysis revealed that PHF6 expression was significantly higher in most cancer types." (PMID 41515604, 2025). "We first evaluated the relevance between PHF6 and prognosis; then, the relevance between PHF6 and immune cell infiltration in pan-cancer were analyzed." (PMID 41515604, 2025). "The expression of PHF6 positively associated with resting-memory CD4+ T cells, while it was negatively correlated with activated NK cells across many cancer types." (PMID 41515604, 2025). "This suggests that distinct mechanisms of PHF6 are involved in tumorigenesis of various cancers." (PMID 41515604, 2025). "Moreover, PHF6 expression showed a strong correlation with cancer heterogeneity and stemness in certain cancer types." (PMID 41515604, 2025). "The results showed that PHF6 was correlated with immune infiltration in 16 types of cancer." (PMID 41515604, 2025). "PHF6 was substantially correlated with prognosis and immune cell infiltration in various cancers." (PMID 41515604, 2025). "Generally, PHF6 was negatively correlated with immune infiltration in most cancers." (PMID 41515604, 2025). "This means that variants in genes only infrequently altered in cancer but which are nonetheless highly useful in diagnosis (e.g. PHF6/PCM1 in case 9, NONO in case 45), can be picked up." (PMID 38997407, 2024). "PHF6 might promote UCEC progression by increasing proliferation of cancer cells and reducing migration of T cells." (PMID 36756714, 2023). "In HeLa cells, knockdown of PHF6 inhibited cancer cell growth and delayed cell cycle." (PMID 36756714, 2023). "Also in cancer, mutations in genes involved in suppression of R-loops have been identified, including BRCA1, PHF6, FIP1L1, BREI, and SRSF1." (PMID 30556094, 2019). "Therefore, we propose that PHF6 could potentially serve as a biomarker for guiding cancer diagnosis and treatment." (PMID 41515604, 2025). "Therefore, targeting PHF6 may offer new therapeutic opportunities for SMARCB1-mutant cancers." (PMID 40115023, 2025).
cancer (continued). "A forest plot was employed to depict the relationship of PHF6 with overall survival (OS) and disease-specific survival (DSS) in different cancer types." (PMID 41515604, 2025). "The association of mRNA expression of predicted target genes (PDCD6, GNG5, PHF6, MAL2, SLC25A15, PTDSS1) with clinicopathological parameters of BLCA patients were analyzed by UALCAN, containing BLCA individual cancer stages and molecular subtypes." (PMID 35503998, 2022). "Multivariate analysis indicated that transcriptional expression of predicted target genes (PDCD6, GNG5, PHF6, MAL2, SLC25A15 and PTDSS1) were significantly correlated with BLCA individual cancer stages and molecular subtypes." (PMID 35503998, 2022). "Still inside the X-chromosome cluster, there are a few cancer-related genes (ATRX, MTCP1, PHF6), but the majority of the genes should be just the results of the X-chromosome inactivation." (PMID 28198667, 2017). "All of these genes are present in the Census database of cancer genes except for the recently discovered cancer genes ATOH1 and PHF6." (PMID 22675565, 2012). "High performance of our resequencing approach is also illustrated by the fact that we identified mutations in known candidate drivers in T-ALL that were included in the collection of known cancer genes such as NOTCH1, FBXW7, PTEN, PHF6, WT1 and PIK3CA." (PMID 22675565, 2012). "Next, we added NuRD complex as a new molecule and ran the “Path Explorer” tool between SET A (NuRD) and SET B (SF3B1B, PHF6, EIF4G3, DCP2, GPR15, miR-490, LINC01222, LINC01718, LINC02036) with the same parameters for diseases: “Cancer”, “Infectious Disease”, and “Reproductive Disease System”." (PMID 38790189, 2024). "Furthermore, we performed a pan-cancer analysis of predicted target genes (PDCD6, GNG5, PHF6, MAL2, SLC25A15 and PTDSS1) by using TIMER." (PMID 35503998, 2022). "The ABL1-I418T, PIK3CB-R231H, CHEK2:c.-4C > T, BRCA2-P3292L, ABL1-E459G, PRPF8-G1796R, PHF6-R274Q, WT1-R435X and ATM-C117Y variants were potentially important cancer variants which were not actionable." (PMID 35896598, 2022). "Additionally, high transcriptional expression of PDCD6, GNG5, PHF6, MAL2, SLC25A15 and PTDSS1 were significantly correlated with BLCA individual cancer stages and molecular subtypes." (PMID 35503998, 2022).
hematologic malignancies (2 papers, 2021 to 2023). "Despite the discovery of PHF6 via its role in BFL syndrome and its prominent role in neurogenesis, mutations of PHF6 have only been identified to date in hematologic malignancies." (PMID 34381727, 2021). "These independent studies indicated that PHF6 may have lineage-specific roles in hematologic malignancies, and possibly via different signaling pathways in different malignancies." (PMID 37393343, 2023).
blood cancer (1 paper, 2025). "Knockout of PHF6 in hematopoietic stem cells could increase the self-renewal ability of cells and drive the development of blood cancer." (PMID 41515604, 2025).
PHF6 also shares sentences with these, for which no sentence is quoted: lymphoma (2 papers); Anxiety (1); B-cell acute lymphoblastic leukemia (1); bacterial infection (1); cervical cancer (1); chronic myelomonocytic leukemia (1); Chung–Jansen syndrome (1); cognitive disorder (1); Danon disease (1); endocrine disorder (1); epilepsy (1); genetic disorders (1); hematopoietic neoplasms (1); Huntington disease (1); infectious disease (1); intellectual disability syndrome (1); Lesch-Nyhan syndrome (1); lung squamous cell carcinoma (1); lymphoid neoplasm (1); mesothelioma (1); mixed phenotype acute leukemia (1); multiple myeloma (1); Myelodysplasia (1); myelofibrosis (1); neurodegenerative disease (1); neurodevelopmental disorder (1); Obesity (1); ovarian serous cystadenocarcinoma (1); Pan (1); pancreatic adenocarcinoma (1).
A further 12 diseases each share a sentence with PHF6 in 1 paper.